PTPRD (protein tyrosine phosphatase receptor type D)
Diseases named in the same sentence as PTPRD in open-access papers (continued):
Sharing a sentence is not in itself a finding about the gene and the disease.
schizophrenia (12 papers, 2011 to 2025). A major psychotic disorder characterized by abnormalities in the perception or expression of reality. "A SNP (rs10977144) located in the protein tyrosine phosphatase, receptor type D gene (PTPRD) was associated with AIWG in a GWAS of Chinese patients with schizophrenia (n = 524, mean age = 26.4)." (PMID 33776816, 2021). "Moreover, PTPRD variants have been recently implicated in schizophrenia and obsessive–compulsive disorder (OCD)." (PMID 38328521, 2023). "The detected variants have not been previously studied; other CTNNA2 and PTPRD variants, however, have been linked to personality traits, such as impulsivity, schizophrenia, and autism, which manifest as unresponsiveness to visual stimuli." (PMID 38328521, 2023). "Moreover, another member of the PTP family, PTPRD (Protein Tyrosine Phosphatase Receptor Delta) has been genetically associated with neurodevelopmental disorders and psychiatric diseases, including ASD, ADHD and Schizophrenia." (PMID 37907504, 2023).
glioma (10 papers, 2014 to 2024). A benign or malignant brain and spinal cord tumor that arises from glial cells (astrocytes, oligodendrocytes, ependymal cells). "PTPRD was shown to be a tumor suppressor, as loss of PTPRD caused aberrant STAT3 activation in gliomas, resulting in glioma progression." (PMID 26079428, 2015). "Their study revealed that loss of expression of PTPRD predicts for poor prognosis in glioma patients." (PMID 25412184, 2014). "For example, in the p16Ink4a knockout RCAS PDGFB/Nestin-tvA glioma mouse model, the downregulation of PTPRD promoted cell proliferation, whereas restoring PTPRD expression in GBM cells resulted in the suppression of cell growth and the induction of apoptosis." (PMID 38339334, 2024). "This study focused on the impact of protein tyrosine phosphatase receptor-δ (PTPRD) in glioma cells, and it was demonstrated that overexpression of PTPRD induces the upregulation of IL-1RAP." (PMID 36499246, 2022). "Yet, it must be noted that this study only assessed in vitro the role of PTPRD and IL-1RAP in gliomas." (PMID 36499246, 2022). "Accordingly, cancer-specific PTPRD mutations abrogated the ability of the phosphatase to dephosphorylate STAT3, leading to aberrant STAT3 activation and promotion of glioma development." (PMID 29228728, 2017). "Recurrent loss or other inactivation of PTPRD has been detected in different human malignancies, and one-copy loss of PTPRD has also been oncogenic in p16Ink4a knockout RCAS PDGFB/Nestin-tvA glioma mouse model." (PMID 35982066, 2022). "Moreover, under upregulation of PTPRD, an increase in the S and G2 cell cycle phases was observed in glioma cells, demonstrating that PTPRD, possibly through the IL-1RAP pathway, promoted the replication of glioma cells and so the proliferation of the tumor." (PMID 36499246, 2022). "In glioma, loss of PTPRD expression accelerated tumor formation, but did not affect cell proliferation." (PMID 29228728, 2017). "In gliomas, loss of PTPRD could cause aberrant activation of STAT3 and is closely associated with glioma progression." (PMID 27738328, 2016).
colorectal cancer (9 papers, 2015 to 2024). A primary or metastatic malignant neoplasm that affects the colon or rectum. "In this study, they found tumor mutational burden and microsatellite instability to be positively correlated with PTPRD mutations in multiple cancer types including non-small cell lung cancer, esophagogastric cancer, and colorectal cancer." (PMID 37731134, 2023). "PTPRD has been found to be somatically mutated in colorectal carcinoma with the R28Q mutation." (PMID 26518340, 2015). "In colorectal cancer, PTPRD suppressed tumor cell migration by promoting cell-cell adhesion." (PMID 29228728, 2017). "For other patients (esophagogastric cancer, bladder cancer, head and neck cancer, colorectal cancer, and unknown primary), the median PFS of PTPRD mutation group was not different from WT (all p ≥0.05)." (PMID 34615542, 2021).
lung adenocarcinoma (9 papers, 2014 to 2025). A carcinoma that arises from the lung and is characterized by the presence of malignant glandular epithelial cells. "In The Cancer Genome Atlas (TCGA) collection, PTPRD is most frequently mutated in cutaneous melanoma (59/344 cases, 17.2%), followed by lung adenocarcinoma (33/230 cases, 14.3%), and stomach adenocarcinoma (30/289 cases, 10.4%)." (PMID 26267899, 2015). "In lung adenocarcinoma (LUAD), exosomal miR-19b-3p secreted by LUAD cells can target macrophage PTPRD, which inhibits PTPRD-mediated STAT3 dephosphorylation in macrophages, resulting in STAT3 activation and M2 polarization." (PMID 40612677, 2025). "Additional significant interaction was identified between KRAS and Protein Tyrosine Phosphatase Receptor Type D (PTPRD), RNA-Binding Motif Protein 10 (RBM10), and Neurogenic locus notch homolog protein (NOTCH1/2/3), reflecting novel immune-related mechanisms in KRAS-mutant lung adenocarcinomas." (PMID 40723270, 2025).
type 2 diabetes (9 papers, 2010 to 2024). "Genome-wide association studies (GWASs) showed that two single nucleotide polymorphisms (SNPs) (rs17584499 and rs649891) in the protein tyrosine phosphatase receptor type D (PTPRD) were associated with type 2 diabetes (T2D)." (PMID 27738328, 2016). "Also, using mouse models and methylation-specific PCR analyses, the hypermethylation -hence silencing- of PTPRD correlated with decreased insulin receptor signaling and type 2 diabetes susceptibility." (PMID 36755664, 2022). "Moreover, a genome-wide association study indicated that single nucleotide polymorphisms in the PTPRD gene are strongly associated with type 2 diabetes." (PMID 31805999, 2019). "A previous study also supports this notion, as it demonstrated that the PTPRD rs17584499 C/T polymorphism is associated with improved postprandial glucose and glycated hemoglobin (HbA1c) levels in Chinese type 2 diabetes patients treated with metformin monotherapy." (PMID 31805999, 2019). "Considering the association between PTPRD polymorphisms and the incidence of type 2 diabetes, PTPRD may be critical for cellular metabolism and re-activating the expression of this gene appears to be important for treating diabetes as well as PTPRD-inactivated cancers." (PMID 31805999, 2019). "Finally, the methylation of PTPRD should also be studied, since there is evidence that this gene can be hypomethylated in leukocytes of patients with type 2 diabetes." (PMID 38339334, 2024). "Furthermore, a type 2 diabetes-related CNV (nsv8414) with marginal significance was detected for PTPRD and intronic SNP rs17584,499 in the gene significantly associated (p = 8.5×10−10) with the incidence of this disease in the Chinese population." (PMID 36755664, 2022). "Consistent with this, PTPRD silencing leads to type 2 diabetes in an experimental mouse model." (PMID 31805999, 2019). "As genetic alterations of PTPRD are related to the occurrence of type 2 diabetes and metformin is a medication for this disease, we aimed to determine whether metformin influenced PTPRD expression in cancer cells." (PMID 31805999, 2019). "The study identified PTPRD and Serine Racemase (SRR) as novel type 2 diabetes susceptibility genes not observed in Japanese and Western population." (PMID 20625434, 2010).
diabetes (8 papers, 2010 to 2024). "PTPRD belongs to the R2A subfamily of protein tyrosine phosphatases (PTPs), which have been implicated in cancer, neural development, and diabetes." (PMID 27738328, 2016). "In a replication study, the PTPRD genetic variant was suggested to be associated with progression to diabetes in Han Chinese, most likely through increased insulin resistance." (PMID 27738328, 2016). "Additionally, PTPRD contained within the chromosome D4 ROH has been associated with progression to diabetes in humans through enhanced insulin resistance." (PMID 33154479, 2020). "These proteins tended be associated with higher risk of incident atrial fibrillation (except for two proteins associated with lower HF risk, SLITRK1 and PTPRD) and variable associations with incident CKD and/or diabetes." (PMID 38225249, 2024). "Given the relationship between PTPRD and diabetes, we decided to treat PTPRD-inactivated cancer cells with metformin." (PMID 31805999, 2019). "We studied Chinese patients with T2D and identified two genes, PTPRD and SRR, that were not previously known to be involved in diabetes and are involved in biological pathways different from those implicated in T2D by previous association reports." (PMID 20174558, 2010).
hepatocellular carcinoma (7 papers, 2014 to 2025). A malignant tumor that arises from hepatocytes. "Downregulation of PTPRD correlates inversely with NAFLD but directly with hepatocellular carcinoma development." (PMID 37595802, 2023). "Aberrations of PTPRD were identified to implicate in chronic lymphocytic leukemia, and PTPRD was demonstrated as the tumor suppressor in hepatocellular carcinoma by regulating the PD‐1/PD‐L1 axis." (PMID 34862763, 2022). "It was also demonstrated that PTPRD could regulate PD-L1 via its effects on STAT3 in human hepatocellular carcinoma, and consequently, enhanced STAT3 activity may support tumor immune evasion." (PMID 39985075, 2025). "In addition, PTPRD regulates PD-L1 signaling in hepatocellular carcinoma." (PMID 36248841, 2022).
obsessive-compulsive disorder (7 papers, 2021 to 2025). A disorder characterized by the presence of persistent and recurrent irrational thoughts (obsessions), resulting in marked anxiety and repetitive excessive behaviors (compulsions) as a way to try to decrease that anxiety. "Genome-wide association studies (GWAS) of either pediatric obsessive-compulsive traits, or Obsessive-Compulsive Disorder (OCD), have identified loci near PTPRD as genome-wide significant, or strongly suggestive for this trait." (PMID 37205689, 2023).
Alzheimer disease (6 papers, 2011 to 2026). A progressive, neurodegenerative disease characterized by loss of function and death of nerve cells in several areas of the brain leading to loss of cognitive function such as memory and language. "Densities of neurofibrillary tangles (NFTs), a major Alzheimer's disease (AD) pathology, display genetic associations with variants in the receptor type protein tyrosine phosphatase D (PTPRD) gene." (PMID 41987927, 2026). "There is further evidence that PTPRD expression may affect the risk of Alzheimer’s disease and other neurodegenerative diseases." (PMID 38328521, 2023). "Moreover, PTPRD is considered one of the candidate genes for Alzheimer’s disease." (PMID 33920310, 2021).
autism spectrum disorder (6 papers, 2014 to 2025). A spectrum of developmental disorders that includes autism, and Asperger syndrome. "A member of the LAR family, PTPδ (encoded by the PTPRD gene), has been associated with attention deficit/hyperactivity disorder (ADHD) and restless leg syndrome, a disorder often comorbid with ADHD, autism spectrum disorder and bipolar disorder." (PMID 24298159, 2014).
bipolar disorder (6 papers, 2011 to 2025). A disorder of the brain that causes unusual shifts in mood, energy, activity levels and the ability to carry out day-to-day tasks. "It has been observed that duplication (71391bp) of the PTPRD gene at 9p23 has been related to an increased risk of suffering bipolar disorder, suggesting that increased PTPRD expression could also be involved in brain pathologies." (PMID 34966732, 2021). "Although duplication in 9p23 has not been reported in association with congenital brain malformation, a smaller dup9p23, affecting solely PTPRD has been detected in a patient with bipolar disorder." (PMID 27087860, 2016).
Ewing sarcoma (6 papers, 2013 to 2017). A small round cell tumor that lacks morphologic, immunohistochemical, and electron microscopic evidence of neuroectodermal differentiation. "We recently reported germline Protein tyrosine phosphatase delta (PTPRD) mutations in a small pilot study in patients with Ewing's sarcoma." (PMID 25119929, 2014). "Here we report three of eight patients (37.5%) with metastatic Ewing sarcoma who harbored germline mutations in the PTPRD gene." (PMID 23800680, 2013). "We identified a novel germline mutation in the PTPRD gene in three of eight patients (37.5%) with metastatic Ewing sarcoma." (PMID 23800680, 2013). "We identified germline PTPRD mutations in three (37.5%) of eight patients with advanced/metastatic Ewing sarcoma." (PMID 23800680, 2013). "Interestingly, somatic and germline PTPRD mutations have been noted in Ewing sarcoma, another bone sarcoma that occurs in children and young adults." (PMID 26510912, 2015). "Of the eight patients with Ewing sarcoma, three (37.5%) had germline mutations in the PTPRD gene." (PMID 23800680, 2013). "Our pilot data suggest that PTPRD germline mutations may play a role in the development of Ewing sarcoma, a disease of young people, and their presence may have implications for therapy." (PMID 23800680, 2013). "However, the role of germline PTPRD mutations in predisposition to Ewing sarcoma, a disease of children, adolescents, and young adults, and the implications of these mutations for therapy with IGF-1R and STAT3 inhibitors warrants further investigation." (PMID 23800680, 2013). "In a small study that sequenced the tumors of a few patients, it was intriguing that PTPRD germline aberrations conferred clinical benefit to patients with Ewing sarcoma who received therapy directed at the IGF1R and mTOR pathway." (PMID 26510912, 2015). "Because phosphorylated STAT3 is frequently upregulated in Ewing sarcoma and PTPRD dephosphorylates STAT3, the role of germline and somatic PTPRD mutations in Ewing sarcoma as well as the implications for IGF-1R targeted therapy warrant exploration." (PMID 23800680, 2013). "To date, while somatic mutations in PTPRD have been reported in diverse tumors, germline mutations of PTPRD have not been investigated in Ewing sarcoma or other cancers." (PMID 23800680, 2013).
Obesity (6 papers, 2013 to 2025). Accumulation of substantial excess body fat. "The VLDLR, IL33 and PTPRD genes were identified as the most interesting genes for obesity-susceptibility within 9p24." (PMID 29441128, 2018). "Given the role of asprosin in metabolism, appetite regulation, and obesity, we measured PTPRD expression while using body weight as a factor for both malignancies." (PMID 38339334, 2024). "In patients with EC, PTPRD is significantly downregulated with obesity, whilst it is also expressed in the peripheral leukocytes." (PMID 38339334, 2024). "In patients with EC, PTPRD is significantly downregulated by obesity." (PMID 38339334, 2024). "Although there is not a bona fide asprosin receptor, PTPRD has been identified as a potential orexigenic receptor for asprosin in hypothalamic AgRP neurons, since genetic ablation of PTPRD leads to loss of appetite, resistance to diet-induced obesity, and lack of response to asprosin." (PMID 40871563, 2025). "For GBM, PTPRD expression was unrelated to obesity, whereas in UCEC, PTPRD was significantly downregulated in UCEC patients with obesity." (PMID 38339334, 2024). "Here, we have also shown that, although the expression is not influenced by the grade or stage of endometrial cancer, PTPRD was significantly downregulated in patients with endometrial cancer with obesity when compared to healthy-weight controls." (PMID 38339334, 2024). "Among them, the upregulated gene BCL2A1 is common in CVD, HTN, obesity, and aging; RNF144B and PTGIS are common in HCL, obesity, aging, and CVD; G0S2, CXCL1, ACKR3, and PTPRD are found in HTN, aging, and CVD; TGFB2, CA12, and MSR1 are familiar in obesity, aging, and CVD." (PMID 36035865, 2022). "However, obesity does not appear to influence the expression status of PTPRD in GBM patients, and the levels of expression amongst these patients are not of a clinical utility as a prognostic biomarker." (PMID 38339334, 2024).
cutaneous melanoma (5 papers, 2015 to 2025). A primary melanoma arising from atypical melanocytes in the skin. "Several PTPs, like PTPRT, PTPRB, and PTPRD, demonstrated a high mutation rate in skin cutaneous melanoma (SKCM) and uterine corpus endometrial carcinoma (UCEC) compared with other cancers due to the higher global mutation burden in the two cancer types." (PMID 36341348, 2022). "In human cutaneous melanoma, PTPRD is deleted or truncated in 9–12% of cutaneous cases, but has not been determined to occur at high frequency in rare histological subtypes." (PMID 30188888, 2018).
endometriosis (5 papers, 2018 to 2025). The growth of functional endometrial tissue in anatomic sites outside the uterine body. "In a GWAS meta-analysis, 13 loci were associated with EC and endometriosis, with one particular locus located within the PTPRD gene." (PMID 40871563, 2025). "In a GWAS meta-analysis, 13 loci were associated with endometrial cancer and endometriosis, with one particular locus located within the PTPRD gene." (PMID 38339334, 2024). "We found that the SNPs rs10739199 (P = 6.75 × 10−5) and rs2025392 (P = 8.01 × 10–5) located at chromosome 9 in PTPRD (protein tyrosine phosphatase, receptor type D) were associated with endometriosis." (PMID 33436679, 2021). "In the present study, we found two endometriosis-associated SNPs, including rs10739199, and rs2025392 of chromosome 9 within the PTPRD gene." (PMID 33436679, 2021). "Recently, a cross-disease GWAS meta-analysis revealed the rs2475335 SNP located within PTPRD to be associated with both endometriosis and endometrial cancer." (PMID 33436679, 2021). "We have reported novel risk loci for the endometriosis-associated gene, PTPRD, that has been implicated in both endometriosis and endometrial cancer through cross-disease GWAS." (PMID 33436679, 2021). "Cross‐disease GWAS meta‐analysis highlighted 13 distinct loci associated at P ≤ 10−5 with both endometriosis and endometrial cancer, with one locus (SNP rs2475335) located within PTPRD associated at a genomewide significant level (P = 4.9 × 10−8, OR = 1.11, 95% CI = 1.07–1.15)." (PMID 29608257, 2018). "PTPRD acts in the STAT3 pathway, which has been implicated in both endometriosis and endometrial cancer." (PMID 29608257, 2018).